NDUFA3 (NADH:ubiquinone oxidoreductase subunit A3)
Description:
Accessory subunit of the mitochondrial membrane respiratory chain NADH dehydrogenase (Complex I), that is believed not to be involved in catalysis. Complex I functions in the transfer of electrons from NADH to the respiratory chain. The immediate electron acceptor for the enzyme is believed to be ubiquinone.
Synonyms: CI-B9; B9
Tractability: Small molecule: an approved drug acts on it; a structure with a bound ligand is known. Antibody: UniProt predicts a signal peptide or a membrane-spanning region. PROTAC: ubiquitination databases record sites on it.
Gene: Protein-coding gene on chromosome 19 (54,102,728 to 54,109,257, forward strand). Ensembl gene ENSG00000170906.
Subcellular location: Mitochondrion inner membrane
Pathways (Reactome):
Metabolism: Complex I biogenesis; Respiratory electron transport
Gene Ontology:
Molecular function: protein binding; NADH dehydrogenase (ubiquinone) activity
Biological process: aerobic respiration; mitochondrial electron transport, NADH to ubiquinone; proton motive force-driven mitochondrial ATP synthesis; proton transmembrane transport
Cellular component: mitochondrial inner membrane; mitochondrion; respiratory chain complex I
Genetic constraint (gnomAD): Loss-of-function variants: 10 observed, 11.52 expected, observed/expected ratio (o/e) 0.87, 90% interval 0.53 to 1.47. The upper end of that interval is the gene's LOEUF score, 1.47, which puts it in group 6 of 6, group 1 being the genes least tolerant of losing a copy. Missense variants: 115 observed, 114.38 expected, observed/expected ratio (o/e) 1.01, 90% interval 0.86 to 1.17. Synonymous variants: 39 observed, 48.14 expected, observed/expected ratio (o/e) 0.81, 90% interval 0.63 to 1.06.
Homologues: Orthologues: chimpanzee NDUFA3 (100% identical), dog NDUFA3 (81% identical), mouse Ndufa3 (81% identical), rat Ndufa3-ps3 (81% identical), rabbit NDUFA3 (80% identical), guinea pig NDUFA3 (77% identical), rat LOC103690298 (76% identical), zebrafish ndufa3 (70% identical), rat Ndufa3-ps1 (68% identical), rat Ndufa3 (64% identical), tropical clawed frog ndufa3 (63% identical).
Diseases named in the same sentence as NDUFA3 in open-access papers:
NDUFA3 is named in the same sentence as 13 diseases in open-access papers, as found by Europe PMC text mining. Sharing a sentence is not in itself a finding about the gene and the disease. The quoted sentences say what the papers report.
breast carcinoma (2 papers, 2022 to 2023). "The following genes were reported to be higher expressed in breast cancer samples of cases compared to controls in two different studies but were reported to be lower expressed in another study: SFRP1, ACTR1B, FASTK, TMEM219, NDUFA3, ATP5I." (PMID 36627894, 2022).
Clear-Cell Renal-Cell Carcinoma (2 papers, 2023 to 2024). "NDUFB1 and NDUFA3 were reported to be associated with the OXPHOS pathway exhibited alterations in clear-cell renal-cell carcinoma and lung squamous cell carcinoma." (PMID 38698303, 2024).
retinitis pigmentosa (2 papers, 2020 to 2023). Retinitis pigmentosa (RP) is an inherited retinal dystrophy leading to progressive loss of the photoreceptors and retinal pigment epithelium and resulting in blindness usually after several decades. "Though no clinical mutations in NDUFA3 have been identified yet, it has been shown that the full deletion of the NDUFA3 gene, along with other genes on chromosome 19, results in retinitis pigmentosa (RP), a disorder caused by photoreceptor cell degeneration." (PMID 33233646, 2020).
asthma (1 paper, 2023). "However, the existing evidence on the role of NDUFA3 in asthma is insufficient, so further investigations are needed." (PMID 37152983, 2023).
Cognitive impairment (1 paper, 2024). Abnormal cognition is characterized by deficits in thinking, reasoning, or remembering. "In participants with cognitive impairment, the expression levels of KEGG:M00146’s NDUFA2, NDUFA3, NDUFA4, NDUFA6, NDUFA7, NDUFA10, and NDUFA12 increased, but the expression levels of NDUFA5, NDUFA4L2, and NDUFAB1 marginally decreased." (PMID 38542318, 2024).
Huntington disease (1 paper, 2025). Huntington disease (HD) is a rare neurodegenerative disorder of the central nervous system characterized by unwanted choreatic movements, behavioral and psychiatric disturbances and dementia. "Furthermore, the transcription factor A, several NADH-ubiquinone oxidoreductases (Ndufa3, Ndufb3) were involved in AD and Huntington’s disease (HD)." (PMID 40545497, 2025).
cancer (2 papers, 2021 to 2023). A tumor composed of atypical neoplastic, often pleomorphic cells that invade other tissues. "As in NAT10 KD cells, the Remodelin-treated cancer cells showed a remarkable decrease in the mitochondrial respiratory genes NDUFAB1, NDUFA3, and NDUFA7." (PMID 37237981, 2023). "Whereas the precise functions of NDUFA3, NDUFA13 (also called GRIM19), COX7A1, COX4I2 and ATP5F1D in oxidative phosphorylation remain somewhat poorly understood, increased expression of NDUFA4L2 is known to drive pro-oncogenic phenotypes in numerous cancer types." (PMID 34782604, 2021).
neurodegenerative disease (2 papers, 2024 to 2025). A disorder of the central nervous system characterized by gradual and progressive loss of neural tissue and neurologic function. "In a TBI rat model, Ndufa3, Ndufb3, and other subunits were identified among the genes correlated with neurodegenerative diseases." (PMID 40545497, 2025). "GO and KEGG analyses of ME7 also identified upregulation of genes related to mitochondrial oxidative phosphorylation, including NDUFS6, NDUFA13, NDUFB7, NDUFA3, and NDUFS5, which are involved in a variety of neurodegenerative diseases." (PMID 37971544, 2024).
NDUFA3 also shares sentences with these, for which no sentence is quoted: cardiac hypertrophy (1 paper); heart failure (1); lung squamous cell carcinoma (1); prostate carcinoma (1); tumor (1).